FTO (FTO alpha-ketoglutarate dependent dioxygenase)
Diseases named in the same sentence as FTO in open-access papers (continued):
Sharing a sentence is not in itself a finding about the gene and the disease.
Obesity (continued). "For example, obesity-associated SNPs within the FTO gene that was known to be related to obesity were shown to form long-range functional connections with IRX328." (PMID 34031368, 2021). "An excessive expression of FTO increases food intake, thereby leading to a positive energy balance linked to obesity." (PMID 34650918, 2021). "Single nucleotide polymorphisms (SNPs) in FTO are the strongest known genetic risk factors for obesity and have been linked with BMI, GDM, T2DM, and eating behaviour." (PMID 33743080, 2021). "The strongest known susceptibility locus for obesity is the fat mass and obesity-associated (FTO) gene." (PMID 33807560, 2021). "Variants of the FTO were suggested as a risk factor for obesity in genome-wide association studies Previous studies addressing the effect of the FTO on dietary intake also showed that variations in FTO were associated with increased energy and fat intake." (PMID 34095191, 2021). "The association between the rs9939609 polymorphism of fat mass and obesity-associated gene (FTO) and risk of colorectal cancer is controversial." (PMID 34650918, 2021). "Potential m6A erasers are alkB homolog 5 (ALKBH5) and fat mass and obesity-associated (FTO, also known as ALKBH9) proteins, which belong to ALKB family of dioxygenases." (PMID 33573224, 2021). "As obesity-risk variants of FTO affect the expression levels of both IRX3 and IRX5, Irx3/5dHet mice serve as a preclinical model mimicking lower IRX3 and IRX5 expression levels in humans." (PMID 34795556, 2021). "Several candidate genes have been identified as being positively associated with BMI and obesity, including the fat mass and obesity associated gene (FTO), and more recently, the brain derived neurotrophic factor (BDNF) gene." (PMID 34867148, 2021). "FTO is associated with fat mass and obesity, while TSH, a crucial hormone regulating energy metabolism, can affect lipid metabolism via a thyroid-independent pathway." (PMID 34258276, 2021). "Genetic variants in the FTO (fat mass and obesity-associated) and PPARγ (peroxisome proliferator-activated receptor-gamma) genes are known to be associated with the incidence of metabolic disease, body mass index and obesity." (PMID 35008459, 2021). "Single nucleotide polymorphism (SNPs) in the FTO gene were associated with other obesity traits (e.g., body weight, leptin levels, body fat, waist circumference)." (PMID 34743743, 2021). "The G allele in FTO variant rs17817449 was considered a risk allele for obesity and obesity-related traits." (PMID 35655906, 2021). "We observed a resistance to weight gain conditional on HFD feeding of rs1421085-DEL82 mice, which is consistent with the notion that nutrition is considered to have the strongest environmental effect on obesity risk at the FTO locus." (PMID 34290091, 2021). "The term “eraser” refers to the m6A demethylase, which mainly consists of fat mass and obesity-associated protein (FTO), and Alk B homolog 5 (ALKBH5)." (PMID 34794452, 2021). "In polygenic obesity, where multiple genes are implicated, single nucleotide polymorphisms (SNPs) in the fat mass and obesity-associated (FTO) gene have been identified as having the biggest impact of a single polymorphism in increasing the risk of obesity." (PMID 33572661, 2021). "Many GWAS have shown the correlation between variants within the FTO gene and obesity and traits related to obesity." (PMID 35655906, 2021). "FTO, whose polymorphisms are strongly associated with obesity and fat mass, exerts the greatest influence on BMI of all known genes." (PMID 34208363, 2021). "A previous study emphasized the influence of genetic risk for obesity and osteoarthritis, but the association is only regulated by the effect on BMI, which is consistent with what is known about the biology of the FTO gene." (PMID 34150765, 2021). "The m6A modification can be reversed by demethylases(also known as “erasers”) such as Fat mass and Obesity-associated protein (FTO) and AlkB homologue 5 (ALKBH5)." (PMID 34350169, 2021).
Obesity (continued). "FTO triggers cancer risk via obesity-related carcinogenesis but the real molecular mechanism has not been elucidated (Chen and Du, 2019)." (PMID 34345232, 2021). "FTO single nucleotide polymorphisms (SNPs) rs17817449, rs1421085 and rs8050136,were determined to be associated with obesity in women with PCOS." (PMID 35655906, 2021). "It is particularly remarkable in the case of BF_kg (r = 0.704, p < 0.001) and BF_% (r = 0.837, p < 0.001), which confirms the FTO expression is associated with a predisposition to obesity." (PMID 34063412, 2021). "FTO (fat mass and obesity-associated) gene, the first identified gene for obesity, is the strongest BMI related genetic factors." (PMID 34675880, 2021). "Various approaches have been employed to attempt explaining the robust association of FTO with obesity." (PMID 34893620, 2021). "Studies suggest FTO polymorphisms increase obesity risk through subtle changes in food intake and preference and affect pathways in the central nervous system that regulate appetite." (PMID 33828129, 2021). "Demethylase FTO is not only associated with obesity but can also regulate mTOR-PGC-1α-mediated mitochondrial synthesis and promote muscle cell differentiation through its m6A demethylase activity." (PMID 33994853, 2021). "The fat mass and obesity-associated (FTO) gene has been recognised as one of the strongest obesity-related genes." (PMID 34578944, 2021). "The FTO gene is one of the most common genes that has been studied around the world in association with obesity." (PMID 34131278, 2021). "This is the case for the obesity-susceptibility alleles in the first intron of the FTO gene, whose connection to obesity has been linked to their role as a cis-regulatory element of the IRX3 transcription factor." (PMID 33909378, 2021). "We only conducted replication analysis with BMI-adjusted associations because the top BMI-unadjusted association is in the FTO gene and a known obesity association." (PMID 33907307, 2021). "The FTO gene was reported in a GWAS to be associated with obesity and obesity traits; therefore, these variants were selected due to their importanceas adiposity mediators." (PMID 35655906, 2021). "The mechanistic basis for the genetic association between FTO and obesity appears to be the disruption of AT-rich interaction domain 5B repressor through the causal variants of FTO." (PMID 35655906, 2021). "A study of the Mediterranean population found that a low education level increased the FTO rs9939609 risk for obesity." (PMID 33668547, 2021). "A study among the German population found that SNPs of the FTO were strongly associated with obesity and T2D." (PMID 34454619, 2021). "Non-coding variations represented by SNPs in the first intron of FTO are the strongest genetic risk factors of polygenic obesity in humans." (PMID 34795556, 2021). "FTO is well-known to promote adipogenesis, and inactivation of the gene encoding FTO protects mice from obesity." (PMID 33922187, 2021). "According to the multiple logistic regression, the FTO gene expression was independently associated with obesity and insulin resistance." (PMID 34063412, 2021). "The obesity-susceptibility gene FTO, which was discovered by a genome-wide association study, has been suggested to be involved in both metabolic and appetite pathways." (PMID 34732214, 2021). "In this regard, a common variation in the FTO gene is reproducibly associated with BMI and obesity from childhood and the genetic load has been linked to several cardiovascular risk factors, highlighting the FTO single nucleotide polymorphism (SNP) rs9939609." (PMID 34208143, 2021). "FTO is the third most common gene according to the number of obesity-associated identified variants in Arabs." (PMID 34131278, 2021). "FTO is the first identified gene providing the strongest genetic association with human non-syndromic obesity." (PMID 33795017, 2021).
Obesity (continued). "Genome-Wide Association Studies (GWAS) detected that common SNPs including rs8050136 and rs9939609 in the FTO gene were strongly associated with fat mass and obesity as well as increased risk for T2DM and thyroid disease." (PMID 34258276, 2021). "Another example is rs56094641-G (near FTO) is associated with increased diabetes, obesity, and dyslipidemia, and this variant was most significantly associated with BMI35." (PMID 33547301, 2021). "For example, FTO genetic variants interact with the genetic and environmental factors that influence obesity risk." (PMID 34836030, 2021). "As a continuation of our previous study, we performed genotyping for FTO rs1421085 and analyzed its association with obesity and dietary intake." (PMID 34743743, 2021). "For instance, the single nucleotide polymorphism (SNP) rs9939609 in the FTO gene has been identified as a common risk factor for obesity and T2D in several populations, including Chileans." (PMID 33909378, 2021). "Recent epidemiological studies also indicated that FTO variants are involved in obesity-associated colon cancer." (PMID 34650918, 2021). "This FTO variant has been extensively studied because it presents a strong association with obesity markers, i.e., a 3-kg increase of additional body weight for each copy of the risk allele in carriers has been documented in several populations." (PMID 34454619, 2021). "The strongest signal was observed on chromosome 16 at the FTO region (index SNP rs9937053, Pmeta = 1.09 × 10− 18), the first GWAS-identified susceptibility gene for obesity." (PMID 33910581, 2021). "Large-scale genetic association studies connecting genetic variants to obesity, as assessed by BMI, have implicated the brain as primary tissue of action, and the FTO haplotype has previously been suggested to affect gene expression in the brain." (PMID 34290091, 2021). "Allelic variants in FTO are assumed to raise obesity risk through impaired central nervous system satiety processing, thereby increasing caloric intake." (PMID 34095191, 2021). "An interesting observation was the relationship between the level of methylation of the FTO gene and its polymorphisms in increasing the risk of obesity." (PMID 34063412, 2021). "One of these genetic loci with a strong effect on obesity and related biological functions such as adipogenesis and energy balance regulation, fat mass, and obesity-associated (FTO) gene has emerged as one of the influential genes with remarkable impact." (PMID 35372458, 2021). "FTO was identified as regulating steady-state energy levels and positively correlating with obesity risk." (PMID 35087575, 2021). "Collectively, these studies suggest that obesity-associated variants of FTO regulate the expression of IRX3 and IRX5 in the hypothalamus and adipose tissue contributing to metabolic changes." (PMID 34795556, 2021). "Our study aimed to explore the underlying mechanisms by which leptin reduces the N6-methyladenosine (m6A) methylation of Plin5 through fat mass and obesity associated genes (FTO) and regulates the lipolysis." (PMID 34638947, 2021). "Claussnitzer demonstrated that the presence of the homozygous C/C obesity-risk alleles in this FTO locus results in the expression of nearby genes IRX3 and IRX5, thus generating less thermogenic adipocyte phenotype." (PMID 34895148, 2021). "The risk allele at the rs1421085 variant in the FTO locus has been connected to cellular consequences in adipocytes and to cellular phenotypes that are relevant for obesity." (PMID 34290091, 2021). "Meanwhile, the fat-mass and obesity-associated (FTO) gene, strongly related to obesity, was found to be associated with risk of Alzheimer’s disease through interaction with the APOE gene, and modulates cholesterol metabolism in the central neural network." (PMID 34501469, 2021). "Common genetic variants in the FTO locus have consistently been associated with obesity mostly among whites of European descent." (PMID 33983957, 2021).
Obesity (continued). "This SNP is an intronic variant in the fat mass and obesity-associated, alpha-ketoglutarate-dependent dioxygenase (FTO) gene and was previously identified to be associated with multiple other traits, including BMI and T2D." (PMID 33907307, 2021). "Here, we report that expression of the fat mass and obesity associated gene (FTO), an RNA demethylase, is downregulated in the hippocampus of patients with MDD and mouse models of depression." (PMID 34836959, 2021). "Several investigations have demonstrated an association between the FTO gene and obesity, implying it as a target gene for obesity investigations." (PMID 34399781, 2021). "FTO is a gene well-known for its association with obesity phenotypes and rs9930333 (FTO) has been associated with BMI in recent adult and child meta-analyses, but not with BP." (PMID 34539733, 2021). "CRYAB mRNA had high expression in thermogenically more potent DN as compared to SC adipocytes and was less expressed in adipocytes that carried the FTO obesity-risk genotype." (PMID 34832860, 2021). "In recent studies, several variants of the FTO gene including rs9930506, rs178117449, rs7202116, rs3751812, rs1421085, and rs9939609 have been related with obesity." (PMID 34399781, 2021). "The FTO obesity variant circuitry, mediated through IRX3 and IRX5, has been linked to adipocyte browning in humans and thus to mitochondrial function." (PMID 34290091, 2021). "In 2007, three independent groups identified multiple SNPs in FTO located on chromosome 16q12.2 to be strongly associated with obesity in both adults and children of European descent." (PMID 33983957, 2021). "Variants in FTO have the strongest association with obesity; however, it is still unclear how those noncoding variants mechanistically affect whole-body physiology." (PMID 34290091, 2021). "Multivariable analysis in the AA cohort revealed that the rs80501360 SNP on chromosome 16 in FTO was associated with obesity (OR 1.40; 95% CI 1.08–1.86; P = 0.01)." (PMID 33983957, 2021). "A pathway for adipocyte thermogenesis regulation has been found to elucidate the potential mechanic basis for the genetic association between FTO and obesity." (PMID 33907307, 2021). "The obesity-linked FTO regulatory circuitry shows cross-species molecular, cellular, metabolic, and organismal conservation." (PMID 34290091, 2021). "Several GWAS studies have demonstrated that genetic variations (SNPs) within the first and second introns of the FTO gene are positively associated with an increased risk of obesity." (PMID 33776928, 2021). "For instance, different genetic variants of FTO, aside obesity promotion, can decrease the risk of depression and be involved in modulating the risk of ADHD (attention-deficit/hyperactivity disorder)." (PMID 33807762, 2021). "The FTO rs9939609 variant is a well-studied SNP that has been associated with higher BMI, risk of obesity, and subsequent T2DM development." (PMID 33729310, 2021). "In both Western and Chinese populations, the FTO polymorphism rs8050136 has been linked to obesity markers (BMI, waist, and hip circumference) and glucose homeostasis." (PMID 34442333, 2021). "Replication of the associations of obesity with FTO and TUB in independent cohorts is warranted given the limited sample sizes." (PMID 33983957, 2021). "FTO is a widely replicated obesity gene and is associated with a variety of obesity traits across diverse ancestries." (PMID 33907307, 2021). "FTO overexpression causes obesity, whereas loss of FTO leads to growth retardation and high early mortality in rodents." (PMID 33461172, 2021). "Dysregulation of N6‐methyladenosine (m6A) methyltransferase components (e.g., Fat mass and obesity‐associated protein [FTO] and methyltransferase‐like 3 [METTL3]) are closely associated with multiple cancer progression, including oral cancer." (PMID 34378866, 2021). "The fat mass and obesity-associated (FTO) gene is known to predispose obesity through an effect on BMI." (PMID 34444990, 2021).
Obesity (continued). "Our results suggest that cultivated hASCs from distinct locations of the human neck still keep their differing propensity for adipocyte browning which is strongly influenced by the presence of the obesity-risk alleles at the FTO intronic locus." (PMID 32316277, 2020). "Amongthe genes, the association of fat mass and obesity-associated gene(FTO) with obesity susceptibility was confirmed." (PMID 32154826, 2020). "The fat mass- and obesity-associated (FTO) gene was initially considered an “obesity gene” when early human studies demonstrated significant associations between its genetic polymorphism and body mass index (BMI)." (PMID 32821265, 2020). "We recommend the replication of these types of studies across different regions of Iran, and also with other variants of FTO to better understand the effect of this gene on obesity and its management." (PMID 32398148, 2020). "Cross-sectional studies indicate that the fat mass and obesity-associated (FTO) rs9939609 gene variant is associated with metabolic syndrome (MetS) primarily in European ancestry." (PMID 32028392, 2020). "Some authors have reported increased FTO expression levels associated with single nucleotide polymorphism (SNP) rs9939609 and an increased risk of obesity and diabetes." (PMID 32916783, 2020). "Genome-wide association studies reported that obesity gene FTO has an association with PCOS, mostly among Asians." (PMID 32050935, 2020). "Among these known genetic polymorphisms, variants of the fat mass and obesity (FTO) gene seem to have the uppermost effect and possible therapeutic implications." (PMID 32534577, 2020). "It is striking that the absence or presence of the FTO obesity-risk allele results in the greatest difference in the gene expression profile (1295 genes) of the differentiated cells." (PMID 32316277, 2020). "The Fat Mass and Obesity-associated (FTO) is one of the genes associated with body mass index and obesity in children and adult." (PMID 31998401, 2020). "Our result showed that the FTO rs9939609 and rs1421085 risk alleles were associated with increased BMI and obesity in the Balinese." (PMID 31915589, 2020). "The rs9939609 variant of fat mass and obesity associated (FTO) gene is linked to metabolic derangement in PCOS." (PMID 32050935, 2020). "Donor selection was based on the presence of obesity-risk SNP of the FTO locus, so donors 1 to 3, 4 to 6, and 7 to 9 carried a T/T risk-free, a T/C heterozygous, or a C/C obesity-risk genotype, respectively." (PMID 32316277, 2020). "Compared to the limited studies on the CLOCK SNP, the SNP, rs9939609, within the first intron of the fat mass and obesity-associated (FTO) gene has been widely investigated for its association with childhood obesity." (PMID 32785234, 2020). "We observed that the risk allele of FTO rs9939609 was associated with greater central and general obesity indices in adults with overweight in Shiraz." (PMID 32398148, 2020). "When comparing associations of SNPs for obesity, all four FTO variants displayed a similar significant association in both the HG and HR groups." (PMID 32384785, 2020). "Another study conducted on the association between FTO gene rs9939609 polymorphism and obesity-related hormones reported that the carriers of the A-allele had higher leptin levels, but this relationship disappeared after adjustment for BMI." (PMID 31996075, 2020). "FTO (fat mass and obesity-associated), a gene associated with the common forms of obesity and with IR in T2D, modulates insulin activity and BMI." (PMID 33142938, 2020). "Variants in the FTO gene also associated with obesity at the p=3x10-4 level, and with hypercholesterolemia with p=1x10-3 level." (PMID 31888951, 2020). "FTO pro-obesity rs1421085 T-to-C single-nucleotide polymorphism (SNP) shifts differentiation program towards white adipocytes in subcutaneous fat." (PMID 32316277, 2020).